TNF (tumor necrosis factor)
Diseases named in the same sentence as TNF in open-access papers (continued):
Sharing a sentence is not in itself a finding about the gene and the disease.
Obesity (continued). "The connection between obesity and immunity has been widely described; under conditions of excess weight, adipose tissue dysfunction promotes an increase in pro-inflammatory cytokines, such as TNF-α and IL-6." (PMID 36839394, 2023). "Obesity was associated with higher levels of IL-12 (P40), MIP-1a in myocardial tissue, while KD alone was associated with higher levels of G-CSF, IL-9, MCP-1, MIP-1a, MIP-1b, RANTES, and TNF-α in myocardial tissue." (PMID 37686855, 2023). "Additionally, in obesity, elevated levels of interleukin 6 (IL-6) and tumor necrosis factor alpha (TNF-α) are observed." (PMID 37375693, 2023). "Since proinflammatory cytokines, including TNF and IL-6, are secreted by white adipose tissue, it is thought that excess adipose mass in patients with RA and obesity may affect treatment response by increasing the level of these cytokines." (PMID 38813042, 2023). "According to multiple research, children, and adults with obesity-associated asthma had higher peripheral blood levels of IL-17A, IL-21, and TNF-α than non-obese patients." (PMID 37377958, 2023). "TNF-α secretion in obesity is increased by leptin and resistin levels." (PMID 37371961, 2023). "Supplementation with G. furcata suppressed the hypertrophy of adipocytes and ameliorated the development of obesity, diabetes, hepatic steatosis, and dyslipidemia, which was accompanied by a dose‐dependent recovery of serum adiponectin and TNF‐α to normal levels." (PMID 36655073, 2023). "Secondly, adipocyte-derived factor, the metabolic alteration in adipose tissue in the setting of obesity, results in an elevated circulating level of adipocyte-derived inflammatory cytokines, enclosing tumor necrosis factor-α, interleukin-6, angiotensinogen, and aldosterone-stimulating factors." (PMID 37464282, 2023). "The condition of obesity leads to the development of an inflammatory environment in the body, characterized by elevated levels of various markers such as C-reactive protein, interleukin-6, and tumor necrosis factor-α in the bloodstream." (PMID 37109333, 2023). "With the occurrence of obesity, the immune cells in adipose tissue infiltrate and produce inflammatory factors, such as tumor necrosis factor-α (TNF-α), interleukin (IL), and C-C motif chemokine ligand 2 (CCL2), promoting local or systemic inflammatory responses." (PMID 37853356, 2023). "During obesity-induced insulin resistance, higher levels of tumor necrosis factor (TNF)-α and interleukin (IL)-6 secreted by adipose tissue may explain the associations of coagulopathy and endothelial dysfunction with insulin resistance." (PMID 37142990, 2023). "In addition, the activation of RAGE promotes a switch in macrophages infiltrating the adipose tissue of mice with diet-induced obesity to M1-type producing inflammatory cytokines, such as tumor necrosis factor-alpha (TNF-α) and interleukin (IL) 1β." (PMID 37446161, 2023). "Dysfunctional adipocytes resulting from obesity disrupt the equilibrium of metabolic mediators, including adiponectin, visfatin, chemerin, resistin, leptin, and inflammatory cytokines, such as tumor necrosis factor alpha (TNF-α) and interleukin-6 (IL-6)." (PMID 37794318, 2023). "First, we identified gene sets related to the function of each obesity-related serum factor: HG/HI (Insr, Irs1, Rps6kb1, Slc2a4, Slc2a5, Slc2a1), TNF-α (Tnfrsf1a, Tradd, Traf2, Fadd), IL-6 (Il6ra, Il6st, Jak1), and fatty acids (PA, LA, Chol; Ffar1, Ffar4, Ppara, Pdk4, Pgc1a)." (PMID 37047207, 2023). "Therefore, excessive production of TNF‐α in adipose tissue and skeletal muscle, two key metabolic tissues, is a consistent feature of obesity in both humans and rodents." (PMID 38107091, 2023). "Conversely, in obesity, higher concentrations of TNF-α are found in the blood and the CNS." (PMID 37383489, 2023).
Obesity (continued). "Another limitation was the exclusive use of hs-CRP to assess the inflammatory profile since this marker can be altered due to other reasons; the use of markers such as TNF-alpha, interleukins, or adipokines would be a better option to provide a view of the inflammation related to obesity." (PMID 37474543, 2023). "TNF-α, increased in subjects with obesity, can inhibit adiponectin, which could also explain the lower expression of adiponectin found in these individuals." (PMID 38068717, 2023). "In an in vitro study, PC12 cells treated with H2O2 reduce pro-inflammatory markers associated with obesity, such as C-reactive protein (CRP), interleukin (IL)-6, and tumor necrosis factor (TNF)-α, leading to reduced oxidativestress-induced neurotoxicity in PC12 cells treated with H2O2." (PMID 37835263, 2023). "A possible hypothesis is the elevated serum levels of IL-6, C-Reactive Protein (CRP), TNF-α, and leptin in obesity may induce inflammatory response in the IVD." (PMID 37959372, 2023). "Moreover, two SNPs in the noncoding parts of TNF gene have been shown to be important for polygenic obesity in Labrador retriever dogs, whereas two exonic SNPs in the MC4R gene have been linked to body weight in Beagle dogs." (PMID 37799139, 2023). "The metabolic syndrome (including hypertension, dyslipidemia, insulin resistance and obesity) had been shown to lead to a chronic pro-inflammatory state and a continuous circulation of cytokines in the body, especially tumor necrosis factor-alpha (TNF-α)." (PMID 37189072, 2023). "In HFD related obesity, adipocytes and macrophages in the adipose tissue generated pro-inflammatory cytokines such as TNFα and IL-6 which could provoke systemic inflammation and contribute to the progression of lung fibrosis." (PMID 36979493, 2023). "TNF-α concentration and receptor affinity may explain the role of this cytokine in obesity pathophysiology." (PMID 37432262, 2023). "Several studies have found circulating concentrations of TNF-α to be elevated in obesity." (PMID 37730940, 2023). "Adipose tissue may contribute to one-third of the total IL-6 in peripheral circulation and secrete TNF-α, and obesity is putative to resemble a low-grade pro-inflammatory state with burden of oxidative stress." (PMID 37104297, 2023). "Adiponectin has also been observed to inhibit TNF-α production, which might be an important target for treating obesity-related asthma." (PMID 37730940, 2023). "Moreover, the adipose tissue obtained from people affected by obesity had higher levels of TNF-α mRNA." (PMID 36765351, 2023). "In the aorta, early overfed rats also showed increased gene expression of the pro-inflammatory cytokines IL-6 and TNFα compared to control rats, possibly as a result of increased infiltration of macrophages into the arterial tissue as is reported in other obesity models." (PMID 37833890, 2023). "A study on 19,372 patients with immune-mediated inflammatory diseases, including inflammatory bowel disease (IBD), RA, spondyloarthropathies, psoriasis, and psoriatic arthritis, examined whether obesity affects response to anti-TNF agents." (PMID 38813042, 2023). "Likewise, a positive relationship was seen between the relative abundance of Firmicutes and increased TNF-α levels correlating with obesity in children." (PMID 37836527, 2023). "Here we review the literature of the signalling events governed by the pleiotropic immune mediator, TNF, and a pathogen sensing system, the inflammasome, during obesity with a focus on the current knowledge regarding cell death regulation in the WAT and its impact on metabolic inflammation." (PMID 36175539, 2023). "Thus, we selected obesity-related in vitro conditions, including glucose, insulin, TNF-α, IL-6, PA, LA, and Chol, to mimic obesity status." (PMID 37047207, 2023). "Importantly, TNF-α can also promote lipolysis in adipocytes and facilitate release of FA, which plays a key role in development of lipid disorder and obesity-induced immunosuppression." (PMID 37266440, 2023).
Obesity (continued). "The role of TNF-α in obesity-related insulin resistance has been recently suggested." (PMID 36986440, 2023). "The role of TNF-α in the development of obesity-related insulin resistance is still controversial." (PMID 37168278, 2023). "Interestingly, obesity participants presented with higher baseline GCF levels of TNF-α than non-obesity participants." (PMID 37798684, 2023). "Although the mechanism leading to impairment of muscle dysfunction in obesity remains unclear, the proinflammatory cytokines present in the muscles such TNFα, IL-6 which are elevated in obesity has been found to be reduced by exercise." (PMID 37576965, 2023). "Obesity and IR promote the transition of macrophages from the anti-inflammatory state M2 to the pro-inflammatory state M1, which leads to the production of interleukin-1 (IL-1), interleukin-6 (IL-6), and tumor necrosis factor-alpha (TNF- α)." (PMID 37893164, 2023). "In fact, fat cells are known to physiologically secrete hormones (leptin, adiponectin and resistin) and pro-inflammatory cytokines including IL-6 and TNF-α, which are recognized to be elevated during obesity, and in turn stimulate the recruitment of immune cell infiltrates." (PMID 37283765, 2023). "Several researchers proved that TNF-α could down-regulate the glucose uptake of endometrium in PCOS patients with obesity." (PMID 37427330, 2023). "The cell-mediated immune response is especially present in obesity when hypertrophic adipocytes produce proinflammatory cytokines, such as IL-6 and TNF-α, which leads to increased vascular permeability and the recruitment of cytotoxic T cells, including T cell phenotypes associated with IR." (PMID 37372966, 2023). "In 1993, the discovery of enhanced tumor necrosis factor α (TNFα) in obese adipose tissue suggested that obesity could be an inflammatory status." (PMID 37138165, 2023). "Thus, the expression of miR-424 has been found to be higher in adipose tissue of children with obesity, whereas TNFα can bind to its promoter region and, consequently, decrease its transcription." (PMID 37672200, 2023). "Therefore, TNF-α has been referred to as the main mediator between obesity-induced inflammation and insulin resistance." (PMID 37763315, 2023). "Obesity induces adipocyte dysfunction, with adipokine secretion and macrophage activation leading to proinflammatory cytokine such as tumor necrosis factor alpha (TNF-α) and interleukin-6 (IL-6) production and the release of anti-inflammatory adipokines such as adiponectin reduction." (PMID 37215204, 2023). "Furthermore, both the baseline and three-month follow-up showed higher levels in obesity participants than in normal-weight participants, indicating that the positive effect of treatment on TNF-α serum levels was offset." (PMID 37798684, 2023). "Long-term obesity may lead to the development of tissue resistance to TNF-α, which contributes to the development of insulin resistance." (PMID 37432262, 2023). "We observed that inflammatory hallmarks such as IFN-γ and TNF-α in γδ T cells were increased both in T2D related obesity or HFD-induced obesity mice using PMA and Ionomycin stimulation, suggesting that obesity impaired γδ T cell homeostasis, which is related to inflammatory cytokine secretion." (PMID 37908738, 2023). "T1DM patients should be given an additional dose of insulin three hours after consumption of high carbohydrate and high-fat food because it can lower the concentration of triglycerides and tumor necrosis factor-alpha (TNF alpha), which has been linked to insulin resistance, obesity, and diabetes." (PMID 38111457, 2023). "Adipose TNF-alpha expression is directly related to the development of IR in obesity." (PMID 38140392, 2023). "A possible interaction between CAMP expression, TNFα, and cfDNA in adipocytes and adipose tissues might provide a novel molecular interface of obesity-related inflammation with adipocyte function." (PMID 37958808, 2023).
Obesity (continued). "Indeed, LPS-treatment and obesity state increased TNFα, IL-1β, and IL-6 expression, both at mRNA and protein levels, in type I TBC." (PMID 37373472, 2023). "Chronic TNF-α exposure encountered in conditions such as obesity may activate alternative and/or compensatory signaling pathways for PAI-1 gene expression in adipocytes." (PMID 38136564, 2023). "In addition to genetic abnormalities, proinflammatory cytokines such as tumor necrosis factor-alpha (TNFα) and interleukin-6 (IL-6) are known to be induced by obesity and high-glycemic diets." (PMID 38024815, 2023). "In the present study, we can suggest that the significantly decreased adiponectin level in the MS group may deteriorate the insulin sensitivity, lipid profile, obesity markers, and TNF-α reactivity." (PMID 36991247, 2023). "However, an increase in TNF-α was observed at 12–13 weeks of gestation, also in women with obesity who developed GDM." (PMID 37891973, 2023). "Based on previous studies, it is possible to hypothesize that the decrease in fat mass, as confirmed in this study, was a determinant of the reduction in serum levels of IL-6 and TNF-α in young women with obesity." (PMID 36976940, 2023). "A hallmark of obesity is chronic low-grade inflammation and the altered secretion of adipokines, inflammatory cytokines, and hormones, including monocyte chemotactic protein-1 (MCP-1), C-reactive protein, IL-6, tumor necrosis factor-α (TNF-α), and adiponectin." (PMID 37629550, 2023). "Another limitation was the nature of our study design, which did not allow the assessment of cause-effect relationships between selected measures of obesity (BMI, WC, RFM, VAI, WHtR) and parameters of chronic inflammation (CRP, TNF-α, IL-6) in perimenopausal healthy women." (PMID 37375693, 2023). "Obesity is associated with a chronic state of low-grade inflammation, characterized by elevated levels of pro-inflammatory markers such as C-reactive protein (CRP), interleukin-6 (IL-6), and tumor necrosis factor-alpha (TNF-α)." (PMID 37623340, 2023). "TNF-α and IL-6, which are generated by adipose tissue as adipokines, encourage low-grade systemic inflammation, which has been linked to chronic, detrimental conditions, such as T2DM, insulin resistance, and obesity." (PMID 38004306, 2023). "Furthermore, inflammatory mediators have been shown to prevent the expansion of BAT in obesity, by promoting cell apoptosis via tumor necrosis factor-α (TNF-α) or reducing tissue proliferation, inhibiting catecholamine signaling." (PMID 36896173, 2023). "To conclude, a few authors have also described obesity-related miRNA dysregulations to be tightly correlated with a multitude of inflammation biomarkers, such as tumor necrosis factor α (TNFα), interleukin 1 receptor antagonist, IL-8, IL-15, procalcitonin, adiponectin, or C-reactive protein." (PMID 37672200, 2023). "TNF-α, a pro-inflammatory cytokine, plays a critical role in insulin resistance due to obesity." (PMID 37367060, 2023). "In people with obesity, the reduction of TNF-α accounts for a reduction in adipose tissue." (PMID 37238961, 2023). "The effect of ADF on TNF-alpha concentrations in adults with obesity was assessed in two trials." (PMID 37139450, 2023). "They play key roles in chronic inflammation-related metabolic diseases including diabetes through the upregulation of tumor necrosis factor (TNF) α, resulting in liver necrosis and the regulation of TG accumulation and the development of fatty liver in the case of obesity." (PMID 37892137, 2023). "In addition, a decrease in hyaluronic acid was observed, which was caused by inflammatory cytokines interleukin (IL)-6 and tumor necrosis factor (TNF)-α that are secreted from macrophages induced in adipocytes due to obesity." (PMID 36289909, 2022).
Obesity (continued). "In particular, OTU479 and OUT545 were significantly positively correlated with the percent of epididymal fat weight, TG, TC, LDL and TNF-α, and negatively correlated with IL-10, and IL-4 levels, revealing that their changes were closely connected with changed obesity in rats." (PMID 35807812, 2022). "Moreover, pro-inflammatory cytokines, such as interleukin-6 (IL-6) and tumour necrosis factor-α (TNF-α), increase in states of both obesity and acute headache attacks, thus contributing to local and systematic inflammation as a prominent feature of headache." (PMID 36686472, 2022). "People with obesity develop inflammation, which is characterized by an increase in the number of macrophages infiltrating adipose tissue and elevated expression and secretion of inflammatory cytokines such as TNF-α, IL-6 and IL-1β." (PMID 35745168, 2022). "In obesity conditions, adiposities release pro-inflammatory cytokines such as TNF-α and IL-6." (PMID 35204193, 2022). "With the aim of furthering understanding about potential metabolic links between obesity and foot pain, this cross-sectional study aims to assess whether CRP, TNF-α, and IL-6 are associated with prevalent foot pain and structural foot disorders." (PMID 35941593, 2022). "This is associated with a shift from M2-like macrophages exerting anti-inflammatory properties to M1-like macrophages secreting pro-inflammatory cytokine (i.e., TNF-α and IL-6) that contribute to a state of chronic low-grade systemic inflammation commonly documented in obesity." (PMID 35187037, 2022). "In obesity, excessive fat accumulation results in overexpansion of adipose tissue, resulting in adipocyte cell death which promotes stimulate Inflammasomes, cytokines (TNF-α, IL-6 and iNOS) and hepatic stellate cells." (PMID 35186751, 2022). "The aim of the present study was to investigate the effect of etanercept (ETA)—an anti-tumor necrosis factor α (TNF-α) monoclonal antibody—on metabolic disorders such as obesity, hypertension, dyslipidemia, and insulin resistance associated with the metabolic syndrome (MS)." (PMID 36418417, 2022). "After adjusting for sex, age, hypertension, blood lipid concentration, and obesity, the level of TNF-α in the case group was higher than that in the control group, following that of IL-10 and IL-4, which indicated that an increased plasma level of TNF-α was significantly associated with sarcopenia." (PMID 36160136, 2022). "Obesity is forming fat tissue with angiogenesis expressing inflammatory factors such as tumor necrosis factor alpha (TNF-alpha), monocyte chemoattractant protein-1 (MCP-1), interleukin 6 (IL-6) and so on which enhance chronic inflammation and will lead to higher risks of cancer." (PMID 36115905, 2022). "R. gnavus were associated with advanced coronary artery diseases (CAD), inflammatory bowel disease, and obesity, which could secrete a complex polysaccharide that potently induces inflammatory cytokine (TNF-α) secretion by dendritic cells." (PMID 36189343, 2022). "During advanced obesity, these macrophages manifest histologically as rings of F4/80+ cells surrounding adipocytes called crown-like structures, and nearly all adipose-tissue derived TNFα is produced by macrophages." (PMID 36105576, 2022). "The mRNA levels of Cd8, iNOS, TNF-α, and IL-1β were increased in obese CCL5 KO mice than in obese WT mice, indicating that CCL5 deficiency also exacerbates liver inflammation in obesity." (PMID 36713454, 2022). "High-fat-diet-induced obesity increases tissue inflammatory cytokines and serum TNFα and IL-6." (PMID 36432430, 2022). "Studies emphasized that myostatin and TNFα are potential candidates for sarcopenia obesity." (PMID 35250869, 2022). "HFD-induced obesity of rats also caused systemic inflammation with an elevation of serum CRP levels and a significant increase in the serum levels of the inflammatory cytokines IL-6 and TNF-α." (PMID 35721744, 2022).